PDX1 (pancreatic and duodenal homeobox 1)
Diseases named in the same sentence as PDX1 in open-access papers (continued):
Sharing a sentence is not in itself a finding about the gene and the disease.
pancreatic cancer (continued). "(vi) Finally, we showed that SLIT2 level could influence PANR within endogenous mouse models of pancreatic cancer (pdx1-cre/KrasG12D/Ink4Af/f) and human PDA xenografts in nude mice, as the SLIT2 level correlated with increased intratumoral nerve fiber density." (PMID 25590802, 2015). "We have followed the Pdx1-Cre;KrasG12D (KC) model to study the progression of pancreatic cancer." (PMID 24947474, 2014). "It is located 200 bp upstream of PDX1, which has been shown to regulate the initiation and the maintenance of pancreatic cancer, playing both the tumor-suppressive and oncogenic roles throughout the different stages of the pancreatic cancer development and progression." (PMID 32456644, 2020). "Importantly, the biodistribution study using human pancreatic cancer mouse model with engineered mutant KrasG12D activation revealed the uptake of 125I-anti-PRR was markedly elevated in pancreas of Pdx1-cre; LSL-KrasG12D mice than WT control littermates at 4 months of age." (PMID 28874965, 2016). "Based on the LSL-KrasG12D/+; Pdx1-Cre (KC) or KPC models, further models of pancreatic cancer have been developed that recapitulate some of the genetic heterogeneity observed in the human disease." (PMID 38421046, 2024).
pancreatic cancer (continued). "We previously showed that a CCK receptor antagonist, proglumide, prevents fibrosis in the pancreas extracellular matrix in Pdx1-Cre/LSL-KrasG12D transgenic mice and also decreased the fibrosis in models of pancreatic cancer." (PMID 36614194, 2023). "To investigate the effect of PDX1 expression on tumor cells in addition to the previously studied PANC-1 line, we used pancreatic cancer cell lines with different degrees of EMT: mesenchymal line MiaPaCa-2 and epithelial line BxPC-3." (PMID 34503200, 2021). "All Pdx1-CreKrasG12DAPCCKO/+p53L/L (PKAP) mice (n = 20) developed a swollen abdomen with a palpable abnormal mass due to ascites fluid and pancreatic tumor burden within 6–10 weeks." (PMID 32586050, 2020). "Next, we asked if API’s immunomodulatory ability occurred in another clinically relevant model of PC (designated KrasG12D; Pdx1-Cre (KC)-HPC mice), making use of a novel pancreatic cancer cell line that mimics human PC due to its expression of mutated Kras." (PMID 33291556, 2020). "For instance, PDX1 was involved in both CASC8-related and VPS9D1-related networks, and also recognized as a key regulator and a potential target in pancreatic cancer." (PMID 31720124, 2019). "Using a mouse pancreatic carcinoma cells derived from the KPC (genotype LSL-KrasG12D;Tp53f/f;Pdx1-Cre) tumor at early passages (P8-10), we tested STA-12-8666 activity against both cellular targets." (PMID 27779106, 2017).
pancreatic cancer (continued). "Inspired by the expressional and functional significance of PD2/Paf1 in various pancreatic cancer cells, we sought to determine the expression pattern of PD2/Paf1 in Pdx1-Cre; Kras G12D (KC) spontaneous mouse model of PC." (PMID 24947474, 2014). "To investigate whether the Acaa1a gene influences the developmental stages of pancreatic cancer, we crossed Acaa1a+/− mice with KPC mice (KrasLSL−G12D/+, Trp53LSL−R172H/+, Pdx1-Cre) to produce Acaa1a+/−/KPC mice, a model for pancreatic cancer." (PMID 40848971, 2025). "Additionally, nuclear FXR expression was also reduced after cholestyramine intervention in the Pdx1-Kras mouse model, indicating that FXR activation was involved in pancreatic cancer progression." (PMID 35326559, 2022). "We investigated whether the effect of reducing migration properties upon overexpression of the PDX1 gene on PANC-1 cells previously demonstrated was also observed in other pancreatic cancer cell lines and human colon cancer cells." (PMID 34503200, 2021). "Moreover, a significant correlation was observed in KPC (KrasLSL-G12D; Trp53LSL-R172H; Pdx1-Cre) and KTC (KrasLSL-G12D/+; Tgfbr2flox/wt; Ptf1a-Cre) autochthonous pancreatic tumors in a genetically engineered mouse model (GEMM)." (PMID 34315872, 2021).
pancreatic cancer (continued). "In this study, by using a transgenic mouse model that can mimic the whole developmental process (from normal acinar cells to invasive PDAC) of pancreatic cancer called LSL-KrasG12D/+; Pdx1-Cre (KC) mice, we demonstrated that the EGFR-HSF1 axis promoted the initiation of pancreatic cancer." (PMID 33422093, 2021). "This will facilitate future use of our Pdx1-Cre-driven conditional PAK4 KO mouse model for testing in vivo potential functions of PAK4 in pancreatic disease models such as for pancreatitis and different pancreatic cancer forms." (PMID 28765528, 2017). "In Pdx1-Cre;LSL-KrasG12D (KrasG12D) mice, physiological levels of KrasG12D induce ductal lesions that recapitulate the full spectrum of human PanINs, putative precursors to invasive pancreatic cancer." (PMID 21304978, 2011). "In addition, the intraperitoneal administration of the inhibitor EHT5372 in Pdx-1-cre LSL/KrasG12D/Ink4a/Arf null B6 mice, a mouse model of pancreatic cancer, resulted in maintenance of their viability for up to 8 weeks, whereas the control mice showed only 30% survival by 8 weeks." (PMID 38675189, 2024). "IPF1/PDX1 regulates downstream molecules such as Neurogenin 3 (NGN3), Forkhead Box A2 (FOXA2), Hepatocyte Nuclear Factor 1 Beta (HNF1B), Fibroblast Growth Factor Receptor 2 (FGFR2IIIB), and Spondin 1, which are involved in pancreatic development, differentiation, and function in pancreatic cancer." (PMID 39239563, 2024). "Finally, metastatic spread of pancreatic tumours to the livers of affected animals is seen in KC, KCD5−/− and KCD6−/− mice as evidenced by lesions with ductal like morphology that exhibit positive staining for the pancreatic marker PDX1." (PMID 35418690, 2022).
pancreatic cancer (continued). "Indeed, Pdx-1-Cre::K-rasLSL-G12D/+::p53LSL-R172H/+::Keap1fl/fl::Nrf2+/+ mice (KPC::Keap1 CKO mice) also exhibited pancreatic atrophy (but no pancreatic tumors; unpublished data)." (PMID 33672789, 2021). "Palb2flox/flox;Pdx1-Cre, Brca1flox/flox;Pdx1-Cre and Brca2flox/flox;Pdx1-Cre animals did not develop pancreatic cancer during the lifespans of these mouse strains, which could be because these mice still express the “floxed” conditional allele." (PMID 31877165, 2019). "Due to the low incidence of pancreatic tumors in the LSL-KrasG12D/+; Pdx-1-Cre mouse model, the clinical relevance of this delay on pancreatic tumor formation or metastasis could not be determined." (PMID 23590467, 2013). "Combined with the overexpression of PDX-1 found in human specimens of pancreatic neuroendocrine tumors and nesidioblastosis, these data demonstrate that PDX-1 is a potential therapeutic target for pancreatic cancer, insulinonoma and islet neoplasia using a novel RNAi effector platform." (PMID 22905092, 2012). "However, small residual human pancreatic tumors had low expression of PDX-1 and marked apoptosis, suggesting the lack of a regenerative capacity of PANC-1 cells following treatment." (PMID 22905092, 2012). "Finally, none of the p16flox/flox; Pdx1-Cre mice under 18 months of age (n=16) developed pancreatic neoplasms, therefore p16 inactivation alone is not sufficient to initiate pancreatic tumorigenesis." (PMID 22113502, 2011). "Recently, we demonstrated that PDX1 ectopic expression results in the reduction of pancreatic cancer line PANC-1 cell motility in vitro and in vivo, and we now provide experimental data confirming the hypothesis that suppression of migration may be related to the effect of PDX1 on cell adhesion." (PMID 34503200, 2021). "In the murine model of spontaneous pancreatic cancer, we found that all LSL: KrasG12D; Pdx1-Cre (KC) mice developed PanIN lesions without invasive carcinoma when they were 18–24 week-old." (PMID 37308977, 2023). "Conditional deletion of Lifr reduces pancreatic tumor progression, but not ADM formation or tumor initiation in an oncogenic KRAS mouse model (Pdx1-Cre; lox-stop-lox-KrasG12D/+; Trp53lox/lox; Lifrlox/lox; lox-stop-lox-Rosa26Luc/Luc)." (PMID 35159011, 2022). "It should also be noted that we did not detect the expression of the PDX1 and PTF1A proteins in cell lysates of all the six pancreatic cancer lines analyzed (data not shown)." (PMID 35884771, 2022).